ADAM10 (ADAM metallopeptidase domain 10)
Diseases named in the same sentence as ADAM10 in open-access papers (continued):
Sharing a sentence is not in itself a finding about the gene and the disease.
glioblastoma (20 papers, 2011 to 2025). The most malignant astrocytic tumor (WHO grade IV). "ADAM10-mediated cleavage of N-cadherin was associated with decreased glioblastoma cell migration, and its cleavage of ligands for the NK cell receptor NKG2D was shown to reduce the immunogenicity of GBM and hepatocellular carcinoma cells." (PMID 41226720, 2025). "Downregulation of PAX2 via siRNA in A498 (renal carcinoma), EAhy (endothelial), T98G (glioblastoma), and SKOV3ip (ovarian carcinoma) cells revealed a nearly total loss of ADAM10 protein as demonstrated by Western blot analysis." (PMID 28367112, 2017). "Moreover, PKC activity induces the translocation of ADAM-10, which is implicated in the cleavage of Notch receptors, to the cell membrane of glioblastoma." (PMID 39752217, 2025). "Reportedly, treatment with ADAM10 inhibitors suppresses the growth of adult and pediatric glioblastoma cells, an effect mediated by blocking ADAM10-dependent release of NLGN3 from neurons." (PMID 41018101, 2025). "It has been shown that activation of the Notch pathway promotes the development of glioblastoma, and α-secretase inhibitors inhibit the growth of glioblastoma by targeting ADAM10/17 and inhibiting the activation of the Notch pathway." (PMID 39634655, 2024). "In Glioblastoma, ADAM10 promote tumor progression by several proposed mechanisms, including Neuroligin-3 release, cleavage of N-cadherin, and depression of NK cell activation." (PMID 36922678, 2023). "Previous reports using commercial glioblastoma cell lines suggest that ADAM10 and ADAM17 inhibition decrease tumour growth and invasiveness but these do not specifically address the behaviour of the tumourigenic cells." (PMID 27541285, 2017). "Reduced motility of glioblastoma cells treated with ADAM10-targeted siRNA has been observed and invasiveness of pituitary adenomas correlated with ADAM10 expression level." (PMID 28367112, 2017). "Low levels of N-Catherine has been associated with less cellular adhesion and when N-cadherin is cleaved by ADAM10 cell migration is promoted in glioblastoma cells." (PMID 23844040, 2013). "PMA also increased degradation of the mature processed form of ADAM17/TACE, but not ADAM10, in HEK293 cells, and promoted the translocation of ADAM10 to the cell membrane in glioblastoma cells." (PMID 21586144, 2011). "In addition to LIM1215 colon xenografts, we also used U251 glioblastoma (GBM) xenografts, since ADAM10 expression is associated with poor prognosis in GBM, where it mediates Notch and other oncogenic signalling." (PMID 35804938, 2022). "Additionally, treatment with inhibitors specific for ADAM10 or ADAM17 increased immune recognition of glioblastoma-initiating cells by natural killer cells." (PMID 28367112, 2017). "In addition, similarly to CADM1, N-cadherin is shed at its ectodomain by ADAM10 in glioblastoma cells, and this process requires PKCα activity." (PMID 24964098, 2014). "Indeed, a study showed that N-cadherin cleavage by ADAM-10 occurred at a significantly higher rate in glioblastoma cells than in normal brain, and it has been further suggested that N-cadherin cleavage is a prerequisite for glioblastoma cell migration." (PMID 34680444, 2021). "To investigate the function of ADAM10 in glioblastoma cells, we used CRISPR/Cas9 to delete ADAM10 from the human glioblastoma cell line U251MG (U251)." (PMID 41226720, 2025). "N-cadherin cleavage is regulated by a protein kinase C-alpha-ADAM10 cascade in glioblastoma (GBM) cells and may mediate GBM cell migration." (PMID 33413403, 2021). "Using the ADAM10 inhibitors GI254023X and INCB7839 in mice, the growth of adult and pediatric glioblastoma cell lines, and PDX were inhibited." (PMID 32265938, 2020). "We, along with others, have previously identified overexpression of the metalloproteinases ADAM10 and ADAM17 in glioblastoma, where increased ADAM10 or ADAM17 expression correlates with poorer prognosis." (PMID 27541285, 2017).
glioblastoma (continued). "GSCs have not only increased expression of ADAMs compared to NSCs but also elevated receptor tyrosine kinases whose ligands are shed by ADAM10 and ADAM17, in particular EGFR, which is often upregulated in glioblastoma." (PMID 27541285, 2017). "We have focused on the role of two closely related metalloproteinases ADAM10 and ADAM17 due to their high expression in glioblastoma and GSCs and their ability to activate cytokines and growth factors." (PMID 27541285, 2017). "ADAM-10 and ADAM-17 are overexpressed in the glioblastoma microenvironment." (PMID 36980765, 2023). "As ADAM10 and ADAM17 are overexpressed in glioblastoma where they can act to increase the EGF concentration in the niche then anti-ADAM10 and ADAM17 treatment may mediate migration out of the niche by reducing local EGF concentrations." (PMID 27541285, 2017). "A negative correlation has been found in glioblastoma between the genetic signature of the epithelial-to-mesenchymal transition (EMT) and that of CD133, suggesting that ADAM10 and ADAM17 inhibition might activate the transition, differentiating the cells and increasing cell migration and invasion." (PMID 27541285, 2017).
atherosclerosis (19 papers, 2017 to 2025). A disease characterized by the build-up of fatty material and calcium deposition in the arterial wall resulting in partial or complete occlusion of the arterial lumen. "In this study, we aimed to determine the causal relevance of endothelial ADAM10 in murine atherosclerosis development in vivo." (PMID 36776254, 2023). "Several studies have already highlighted that ADAM10 is associated with atherosclerosis development in humans." (PMID 37108478, 2023). "Many ADAMs have been linked with both the early and advanced stages of atherosclerosis, an example of which ADAM10 elevation was found in unstable atherosclerotic plaque tissues." (PMID 30926762, 2019). "However, a limiting factor in the evaluation of this causal role of ADAM10 in atherosclerosis in vivo is the fact that full-body Adam10-deficient mice are embryonically lethal, making it impossible to investigate the global effect of ADAM10." (PMID 37108478, 2023). "In summary, reduced LOX-1 shedding in ADAM10-deficient endothelium may render these mice more susceptible to oxLDL-induced inflammatory processes and atherosclerosis." (PMID 36776254, 2023). "Contrasting this role of myeloid ADAM10 in atherosclerosis formation, endothelial Adam10-deficiency resulted in a markedly increased atherosclerotic lesion size, which coincided with an increased necrotic core and reduced macrophage content, though lesional collagen content was unaffected." (PMID 37108478, 2023). "Compared with the sh-NC group, the levels of IL-1β and TNF-ɑ in the sh-ADAM10 group were significantly decreased (p < 0.05), suggesting that silencing ADAM10 could inhibit the inflammatory response associated with atherosclerosis." (PMID 30926762, 2019). "In order to further investigate the effects associated with CDKN2B-AS1 and ADAM10 on the progression of atherosclerosis in vivo, the ApoE knockout mice recruited for the purposes of the study were placed on a high-fat diet for 10 weeks in order to establish the animal models of atherosclerosis." (PMID 30926762, 2019). "Hence, the current study set out to investigate the effects associated with the lncRNA CDKN2B-AS1 as well as ADAM10 on atherosclerosis." (PMID 30926762, 2019). "No significant changes in relation to the serum levels of IL-1β and TNF-ɑ in the M-oe-CDKN2B-AS1 + oe-ADAM10 group were detected, highlighting the inhibitory role of CDKN2B-AS1 in the stimulating effect of ADAM10 on the inflammatory response associated with atherosclerosis." (PMID 30926762, 2019). "Existing literature has linked relatively high levels of ADAM10 expression with atherosclerosis." (PMID 30926762, 2019). "In this study, the effects of white tea on ADAM10/17 enzyme activities, which play an important role in the atherosclerosis process, were investigated for the first time, and it was found that it decreased the activity of these enzymes." (PMID 39770544, 2024). "For example, ADAM10 was shown to be involved in neurodegenerative diseases, autoimmune diseases, atherosclerosis, and cancer." (PMID 39329961, 2024). "Our study results show that propolis can effectively reduce atherosclerosis-related inflammation and dyslipidemia through ADAM10/17 inhibition." (PMID 38931216, 2024). "ADAM10 has a large repertoire of substrates, many of which are involved in the pathogenesis of atherosclerosis, including lectin-like oxidized low-density lipoprotein (oxLDL) receptor 1 (LOX-1)." (PMID 36776254, 2023). "The membrane-bound chemokines CXCL16 and CX3CL1 are not only shed by ADAM10/ADAM17 in the kidney but also play an important role in the context of atherosclerosis." (PMID 37108478, 2023). "Taken together, this study demonstrates that endothelial ADAM10 is a protective factor in atherosclerosis, on the one hand by restraining plaque neovascularization and intraplaque hemorrhage, and on the other hand by limiting inflammation." (PMID 36776254, 2023).
atherosclerosis (continued). "In several CVDs, the ADAM10- and ADAM17-mediated cleavage of adhesion molecules has been implicated in atherosclerosis and vascular remodeling." (PMID 37762417, 2023). "On the other hand, miR-25-3p attenuates oxidized low-density lipoprotein-mediated coronary vascular endothelial cell inflammation by targeting Adam10 in ApoE–/– mouse models of atherosclerosis." (PMID 35069547, 2021). "In order to identify the role of ADAM10 in atherosclerosis, its expression was investigated at both the tissue and cellular levels." (PMID 30926762, 2019). "Consistently, a previous study concluded that the abnormal expression of ADAM10 plays a vital role in the progression of atherosclerosis with reports implicating it in the macrophage inflammatory process." (PMID 30926762, 2019). "The present study also identified that lncRNA CDKN2B-AS1 recruited DNMT1 to ADAM10 promoter region, initiated methylation and inhibited ADAM10 expression, thereby diminishing atherosclerosis and promoting cholesterol efflux." (PMID 30926762, 2019). "This study aimed to investigate the role of lncRNA cyclin-dependent kinase inhibitor 2B antisense RNA 1 (CDKN2B-AS1) in atherosclerosis via its function in A disintegrin and metalloprotease 10 (ADAM10)." (PMID 30926762, 2019). "The data collected during our study further identified a relationship whereby the overexpression of lncRNA CDKN2B-AS1 induced ADAM10 gene methylation to inhibit its expression, highlighting an underlying regulatory mechanism of CDKN2B-AS1 in atherosclerosis." (PMID 30926762, 2019). "ADAM10 downregulation by fish oil has been shown to slow down the development of atherosclerosis in male mice." (PMID 30926762, 2019). "Macrophages express relatively high levels of the Notch-promoting Tspan14, highlighting the macrophage Tspan14/ADAM10 complex as a potential therapeutic target for maintaining plaque stability in atherosclerosis." (PMID 30013551, 2018). "Besides a crucial role in CKD, ADAM10 and ADAM17 have been more elaborately studied in the context of CVD, particularly in atherosclerosis, the main underlying cause of CVD." (PMID 37108478, 2023). "Combined, it could be clearly demonstrated that ADAM10 plays a key role in atherosclerosis formation in a cell-specific manner." (PMID 37108478, 2023). "However, cell-specific models have so far proven to be highly useful to at least elucidate the role of cell-specific ADAM10 in atherosclerosis formation." (PMID 37108478, 2023). "However, further studies are still needed to also explore the role of ADAM10 expressed in other cell types (such as SMCs) in atherosclerosis formation." (PMID 37108478, 2023). "Previous research pointed out that CDKN2B-AS1 could impede ADAM10 expression in atherosclerosis, which decreased inflammation response and contributed to cholesterol efflux." (PMID 33298110, 2020). "Key observations indicated that overexpressed CDKN2B-AS1 could potentially promote cholesterol efflux in atherosclerosis by downregulating ADAM10 via DNMT1-mediated ADAM10 DNA methylation." (PMID 30926762, 2019). "The current study presents evidence confirming that the overexpression of lncRNA CDKN2B-AS1 could inhibit the progression of atherosclerosis by downregulation of ADAM10." (PMID 30926762, 2019). "Considering that CDKN2B-AS1 was downregulated and ADAM10 was highly expressed in patients with atherosclerosis, the following experiments were conducted to investigate the mechanism by which CDKN2B-AS1 could inhibit ADAM10 expression." (PMID 30926762, 2019).
atherosclerosis (continued). "However, whether endothelial ADAM10 contributes in the pathogenesis of atherosclerosis or this increased expression reflects a disease-related response, e.g., an attempt to dampen/limit plaque neovascularization has not been investigated so far." (PMID 36776254, 2023). "A previous study highlighted the potential of lncRNAs could be novel players in atherosclerosis Existing literature has suggested that ADAM10, a mediator of endothelial cell function regulated by vascular endothelial growth factor, is closely related to the development of atherosclerosis." (PMID 30926762, 2019). "Thus, we subsequently tested the hypothesis that the overexpression of lncRNA CDKN2B-AS1 via binding to DNMT1 can reduce atherosclerosis and promote cholesterol efflux by downregulating ADAM10." (PMID 30926762, 2019). "Although ADAM10 and ADAM17 have been extensively studied in contexts such as atherosclerosis, the role of ADAM8 in sepsis-induced cardiac dysfunction remains poorly understood." (PMID 41169382, 2025). "In particular, ADAM10 and ADAM17 have been extensively studied and are confirmed to be closely related to cardiovascular diseases such as atherosclerosis." (PMID 41169382, 2025). "This study evaluated in vivo for the first time the effects of white tea on ADAM10 and ADAM17 enzyme activities, which play an important role in the pathophysiology of atherosclerosis." (PMID 39770544, 2024). "miR-654-3p was found to reduce inflammation by targeting ADAM10 and RAB22A (both promoters of atherosclerosis) and TNFRSF9 (TNF receptor family member 9)." (PMID 39201485, 2024). "ADAM10 and ADAM17 shed partly overlapping substrates, although they appear to have opposite functions in atherosclerosis." (PMID 37108478, 2023). "As suggested by previous studies, the ADAM10 and ADAM17 downregulate STZ-induced type 1 diabetes mellitus in rats, and the mechanism is related to atherosclerosis." (PMID 36452319, 2022). "Based on the important role of ADAM10 and ADAM17 in inflammation and the related leukocyte recruitment studied mainly in in vitro settings, it is highly likely that these ADAMs also play a crucial role in atherosclerosis formation in vivo." (PMID 37108478, 2023). "There were no significant changes in the M-oe-CDKN2B-AS1 + oe-ADAM10 group, indicating that overexpression of CDKN2B-AS1 inhibited atherosclerosis, overexpression of ADAM10 promoted atherosclerosis, and overexpression of CDKN2B-AS1 can reverse the effect of ADAM10 on atherosclerosis." (PMID 30926762, 2019). "Finally, pinpointing ADAM10 as a cause of IR-induced endothelium permeability offers a new possibility for prevention of IR-induced CVD, especially when animal experiments show that anti-inflammatory or anti-coagulant therapies are not successful in preventing IR-induced atherosclerosis." (PMID 29137243, 2017).
colorectal cancer (18 papers, 2013 to 2026). A primary or metastatic malignant neoplasm that affects the colon or rectum. "ADAM10 is a transmembrane protein involved in proteolysis and cell adhesion, and has been implicated in the pathogenesis or progression of several cancers, including uterine, ovarian, gastric and colorectal cancer." (PMID 23799912, 2013). "Previous studies have indicated that ADAM10 can cleave mMICA to generate sMICA, thereby promoting tumorigenesis in colorectal cancer." (PMID 40726981, 2025). "In colorectal cancer, miR-365a-3p reduced the cell growth and metastasis by regulating ADAM10/JAK/STAT signaling." (PMID 34991445, 2022). "ADAM10 and ADAM17 have a role in inflammation and diseases associated with inflammation, such as diabetes, cardiovascular diseases (CVD) or cancer, e.g., colorectal cancer (CRC)." (PMID 36286024, 2022). "MiR-365a-3p inhibits metastasis and growth of colorectal cancer by targeting ADAM10/JAK/STAT signaling." (PMID 34789263, 2021). "By serological proteome analysis we identified the surface membrane protein ADAM10, a metalloproteinase that has a role in epithelial-tumor progression and invasion, as a target of the immune response in colorectal cancer (Crc)." (PMID 27517630, 2016). "ADAM10 in particular is the sheddase being largely responsible for ectodomain shedding of E-cadherin and LI-cadherin in colorectal cancer cells (unpublished data) and four of the five cancer cell lines displayed higher ADAM10 levels than HPDE cells." (PMID 24625754, 2014). "tRF-3021a is highly expressed in colorectal cancer, and by upregulating ADAM10 protein expression, cleave membrane MICA forms more soluble MICA, blocking the cytotoxic effect of NKG2D activated receptors in NK cells, and ultimately leading to immune escape in colorectal cancer." (PMID 40726981, 2025). "Serum ADAM10 levels have also been evaluated as a biomarker for malignancy like colorectal cancer." (PMID 35705192, 2022). "The tetraspanin-29/ADAM10/Notch pathway also plays an important role in colorectal cancer." (PMID 36286024, 2022). "The analysis showed that serum levels of ADAM10 and ADAM28 are significantly higher in patients with colorectal cancer and correlate with histopathological grading and with presence of distant metastases." (PMID 31565100, 2019). "This, in turn, facilitates colorectal cancer progression through an NKG2D receptor-mediated immune escape mechanism, resulting in the inhibition of NK cell activation by promoting MICA shedding via ADAM10." (PMID 40726981, 2025). "Quantitative PCR of ADAM10 mRNA expression confirmed comparable ADAM10 expression to that of a larger set of normal and tumour tissues from a cohort of 19 colorectal cancer patients, in which expression was independent of tumour stage." (PMID 35804938, 2022). "In addition, expression levels of ADAM10, ADAM17, and ADAM19 were elevated in human colorectal carcinoma biopsy specimens compared to adjacent non-tumorous tissues." (PMID 33043016, 2020).